IL5 (interleukin 5)
Diseases named in the same sentence as IL5 in open-access papers (continued):
Sharing a sentence is not in itself a finding about the gene and the disease.
nasal polyps (continued). "In this regard, it has been shown that molecular antibodies targeting IL-5 are able to disrupt IL-5-mediated intercellular networks involving eosinophils, mast cells, and airway epithelial cells, which drive nasal polyp development." (PMID 37240477, 2023). "Supplementaryly, CST1 enhances eosinophil activation and recruitment by inducing IL-5 production in nasal polyp cells isolated from patients with eosinophilic chronic rhinosinusitis." (PMID 36776870, 2023). "Nasal polyps show increased levels of mediators important for eosinophil accumulation and survival (e.g., IL-5 and IL-13) in comparison to healthy sinonasal tissue." (PMID 36986875, 2023). "Novel biologic agents blocking the production or action of such cytokines, including, for instance, IL-5, IL-5Rα, IL-33 and immunoglobulin (Ig)E, have been developed and examined for treatment of chronic rhinosinusitis-related nasal polyps." (PMID 37375083, 2023). "The α-toxin induces nasal polyp cells to produce large amounts of IL-5, IL-13, IFN-γ, IL-17A, and IL-10, which are involved in the inflammatory response." (PMID 35878202, 2022). "SEB induces Th1 and Th2 pro-inflammatory responses in nasal polyps and increases the serum concentrations of IL-4, IL-5, and IFN-γ." (PMID 35878202, 2022). "IL-5 and IL-13 levels were significantly increased in the nasal polyps of patients with eCRSwNP (both P < 0.001) or noeCRSwNP (both P < 0.001), compared with control tissues." (PMID 35747690, 2022). "S. aureus binding to TLR 2 directly induces the release of epithelial cell-derived cytokines and promotes the expression of TSLP, IL-5, IL-13, and IL-33 in nasal polyp tissue." (PMID 35878202, 2022). "IL-5 plays a central role in chronic inflammatory response in nasal polyposis by inducing the accumulation of a large quantity of eosinophils within the polyps." (PMID 35008843, 2021). "When the ethmoid and nasal polyp tissues of patients with CRS are examined, local T cell infiltration, mediators such as IL-4 and IL-5, and Th2-type cytokine profile dominance were observed in the ethmoid mucosa and nasal polyps of the patients with CRS." (PMID 34212158, 2021). "Another study on the relationship between MMP and cytokines in nasal polyps reported a significant correlation between IL-5 and TIMP-1, suggesting their potential role in the maintenance of homeostasis in nasal polyp." (PMID 33477617, 2021). "According the results of a meta-analysis, anti-IL5 therapy with mepolizumab induces a reduction in nasal polyp score in patients with CRSwNP." (PMID 35387050, 2021). "The IL-5 antibody reslizumab has been tested in several placebo-controlled studies in asthma patients with comorbid nasal polyps and has been shown to improve quality of life." (PMID 33426426, 2021). "In fact, treatment with anti-IL5 (mepolizumab) has shown a reduction in both nasal polyp and blood eosinophils, and a significant improvement in CRSwNP patients, resulting in better prognosis." (PMID 34055883, 2021). "Anti-IL5 (reslizumab and mepolizumab) therapies used in severe eosinophilic asthma have improved the nasal polyp score in patients suffering from severe nasal polyposis being refractory to corticosteroid therapy." (PMID 32467765, 2020). "Nasal polyps and use of montelukast were more common in the anti-IL5/IL5R group than in the anti-IgE group." (PMID 32467765, 2020). "The target proteins, interleukin (IL)-4, IL-5, IL-13, and IgE were previously identified as key mediators in studies using nasal polyp tissues to measure and to interact in ex-vivo settings." (PMID 31452831, 2019). "Reslizumab was shown to reduce nasal polyp size, but only in patients with elevated nasal IL-5 levels." (PMID 30781703, 2019). "CXCL8 (IL-8), which attracts neutrophils and eosinophils into the nasal mucosa, provided these have been previously activated by IL-5, plays a further role in nasal polyp inflammation." (PMID 29564208, 2018).
nasal polyps (continued). "In summary, anti-IL-5 has the capacity to reduce the size and number of nasal polyps in patients with CRSwNP, and to reduce the need for surgery." (PMID 29682504, 2018). "IL-5 is upregulated in nasal polyps and plays an important role in the pathogenesis of nasal polyps." (PMID 29564208, 2018). "Messenger RNA (mRNA) levels of TGF-β, IL-5, IL-6, and iNOS in the frontal recess, ethmoid mucosa and nasal polyps were assessed by quantitative RT-PCR analysis." (PMID 28464955, 2017). "In fact, nasal polyp tissue, when compared with adjacent inflammatory nasal mucosa, was shown to express higher levels of IL-5 and lower levels of TGF-β mRNA." (PMID 28464955, 2017). "After reviewing a total of 115 samples (15–20 samples per group), the mucosal presence of Staphylococcus aureus was correlated with IL-5 and SE-IgE positive chronic rhinosinusitis with nasal polyps and nasal polyps from cystic fibrosis patients." (PMID 26275068, 2015). "The majority of patients with CRSwNP in the United States and Europe have pronounced infiltration of eosinophils and expression of interleukin-5 (IL-5) in nasal polyps." (PMID 26594227, 2015). "In nasal polyps, IL-5 correlated highly with other Th2 cytokines: eotaxin, MCP-1, MCP-4, TARC, IL-4 and IL-13." (PMID 26132710, 2015). "Only in CRSwNP, a significantfraction of T cellsproduced the Th2 cytokinesIL-4 and IL-5, while nasal polyps from CF patients were characterized by a higher CD4/CD8 T cell ratio and an increased number of Th17 cells." (PMID 24911279, 2014). "IL-5 is an important cytokine in patients with CRSwNP as it is responsible for delaying eosinophilic apoptosis in nasal polyps." (PMID 25133733, 2014). "Nasal polyp tissues showed significantly (P ≤ 0.01) altered gene expression values for over 4,000 genes and a significant increase of Th2 cytokines (IL-4, IL-5, IL-10, and IL-13) compared to the inferior turbinate (data not shown)." (PMID 24995349, 2014). "The infiltration of inflammatory cells, particularly eosinophils (EOSs) and T lymphocytes, and abnormalities in the cytokines, including the upregulation of interleukin (IL)-4, IL-5 and IL-10, are characteristics of the immune dysfunction of nasal polyps." (PMID 23737902, 2013). "In nasal polyp tissues, DCs induced T cells to secrete IL-5 by increasing the amount of EOS infiltration." (PMID 23737902, 2013). "In previous studies, the high level of IL-5 has been identified to be one of the most significant demonstrably correlative factors with nasal polyps and one of the promotory factors in EOS infiltration." (PMID 23737902, 2013). "As the nasal polyps develop, EOSs replace the Th2 cells to become the most significant source of IL-5." (PMID 23737902, 2013). "SEB resulted in a significant release of IL-1, TNF-α, IFN-γ, Il-2, IL-5 and IL-17 from nasal polyp tissue, indicating the stimulation of all prominent T helper cell populations." (PMID 22272213, 2012). "Patients with CRSwNP had higher total IL-5 and IgE levels in nasal secretions, nasal polyp homogenisates, and blood serum than in controls." (PMID 22927869, 2012). "The specific knowledge on the role of IL5 in CRS with NP as discovered previously and the possibility of IL5 antagonism in vitro led to the clinical application of humanized anti-IL5 antibodies for the treatment of nasal polyposis." (PMID 21984922, 2011). "For example, several investigators have proposed that IFN-γ, IL-4, and IL-5-producing lymphocytes are found in nasal polyps, and that nasal polyps possess a mixed pattern of Th1/Th2 cytokines." (PMID 19250527, 2009). "More recently, a Th2-skewed eosinophilic inflammation with high levels of IL-5 and IgE was described in CRSwNP, and decreased Foxp3 mRNA was demonstrated in nasal polyps." (PMID 19250527, 2009).
nasal polyps (continued). "Upon activation, ILC2s release IL-5 and IL-13, promoting eosinophilic inflammation, goblet cell hyperplasia, mucus hypersecretion, and tissue remodeling, all central features of chronic rhinosinusitis with nasal polyps (CRSwNP) and severe allergic rhinitis." (PMID 41752128, 2026). "Eighty-five percent of nasal polyps are infiltrated by eosinophils marked by interleukin-5 (IL-5)." (PMID 40497171, 2025). "Biological therapies such as anti-IgE monoclonal antibody, IL-4 receptor alpha subunit antagonist, and anti-IL-5 are promising treatments for nasal polyps and could significantly improve olfaction." (PMID 38903957, 2024). "Furthermore, ILC2 derived from nasal polyp tissue also have the potential to produce more IL-5 and IL-13 compared to ILC2 from the nasal mucosa of healthy controls." (PMID 38540714, 2024). "The severity of the disease can be correlated with nasal polyps enriched in eosinophils/IL-5 and, although ≥ 10 eosinophils per high power field are considered enough to determine an eosinophilic CRS, this cut-off value, the biopsy method, and the sampling location are still a matter of debate." (PMID 39373848, 2024). "Studies performed involving the administration of humanized monoclonal antibodies against IL-5, namely reslizumab and mepolizumab, found that there was significant reduction in the size of nasal polyps as well as peripheral blood eosinophil level, which reduced the necessity for revision surgeries." (PMID 36832203, 2023). "Approved biological therapies for nasal polyps include omalizumab, [a monoclonal antibody to immunoglobulin E (IgE)], mepolizumab [a monoclonal antibody to interleukin-5 (IL-5)], and dupilumab [a monoclonal antibody to the IL-4 receptor alpha subunit, blocking IL-4 and IL-13 activity]." (PMID 36970067, 2023). "They found that negative, moderate, and high IL-5 clusters were associated with clinical phenotypes of CRSsNP, mixed CRSsNP/CRSwNP, and an almost exclusively nasal polyp phenotype, respectively." (PMID 36832203, 2023). "Moreover, IL-5 expression is up-regulated in nasal polyp tissue, and high IL-5 levels correlate with more severe nasal polyposis." (PMID 37240477, 2023). "Several studies have reported increased IL-5 mRNA and protein in nasal polyp tissue." (PMID 35008843, 2021). "Overall, biologic therapy with mAbs targeting IgE (omalizumab), IL-4Rα (dupilumab), or IL-5 (reslizumab, mepolizumab) led to the improvement of several clinical outcomes, including reduction size of nasal polyps, favorable impact on quality of life, nasal airflow capacity and smell." (PMID 35387050, 2021). "The hypothesis on the role of this antibody was derived from a former study in 1997 showing that IL-5 protein is increased in nasal polyps and that this cytokine correlates to eosinophil presence." (PMID 31452831, 2019). "AFRS-/EFRS-related nasal polyps exhibit a significantly higher level of IgE and IL-5." (PMID 29564208, 2018). "IL-5 was measured in nasal secretions in mepolizumab-treated subjects with nasal polyposis to address this issue, initially demonstrating that levels above 40 pg/mL were predictive of a clinical response, although this was not confirmed in a subsequent larger-scale study conducted by the same group." (PMID 29682504, 2018). "Anti-IgE stimulation of nasal polyps resulted in an increase in IL-5 within 6 hours; this release could significantly be suppressed by corticosteroid pretreatment." (PMID 22272213, 2012). "Anti-IL-5 and anti-IL-5Rα in real-life studies have shown to significantly reduce eosinophils number in nasal polyps, the latter with a complete reduction in eosinophils- and neutrophils-infiltrated cells, with a significant reduction in the nasal polyp score (NPS) after 6 months." (PMID 37108417, 2023).
nasal polyps (continued). "One of the hallmarks of nasal polyposis is epithelial barrier dysfunction since the expression of tight junction and cell adhesion proteins is significantly thwarted, compared to healthy individuals, as a direct result of IL-5 on airway epithelial cells expressing the IL-5 receptor (IL-5R)." (PMID 35743760, 2022). "Finally, dispersed nasal polyp cells are reported to produce IL-5 and IL-13 when exposed to SEB." (PMID 35264183, 2022). "Enriched blood and nasal polyp ILC2 cultured with TNF demonstrated a time- and dose-dependent production of IL-5 and IL-13, which was further enhanced in the presence of TSLP or IL-33 in vitro." (PMID 38540714, 2024). "Conversely, a significant correlation has been observed between the prevalence of ILC2s and IL-5-producing ILC2s and the concentrations of IL-5, CCL24, and IgE identified within nasal polyp tissues." (PMID 38680486, 2024). "This is reflected at the cellular and molecular level; nasal polyps from patients with AERD have been shown to have over three times as many eosinophils and higher IL-5 concentrations when compared to polyps from subjects with non-AERD CRS." (PMID 37095527, 2023). "Gevaert and his team found that using anti-IL-5 treatment in patients with CRS with nasal polyps (CRSwNP) reduces eosinophilic infiltration, thereby reducing the size of nasal polyps." (PMID 38022554, 2023). "This, in turn, results in the suppression of staphylococcal enterotoxin B-induced IL-5, IL-13, IFN-γ, and IL-17 production in nasal polyp cells." (PMID 36986875, 2023). "In this study, we found that IL-5, IL-13, ECP, and eotaxin levels were significantly increased in the nasal polyps of patients with eCRSwNP or noeCRSwNP, whereas IL-4 levels were only increased in patients with eCRSwNP." (PMID 35747690, 2022). "Levels of IL-4, IL-5, IL-13, and ECP and the eotaxins CCL11, CCL24, and CCL26 were elevated in the nasal polyps of patients with eCRSwNP or noeCRSwNP." (PMID 35747690, 2022). "The expression of IL-5, POSTN and IL-33 mRNA was determined in sinonasal mucosal samples and in nasal polyp tissue by real-time PCR." (PMID 35752781, 2022). "The stimulation of cultured epithelial cells with Th2 cytokines, IL-4 and IL-5, resulted in higher CCL17 expression in nasal polyp epithelial cells when compared to normal ethmoid tissue." (PMID 35455762, 2022). "In an experimental study using organ culture of nasal polyps, S. aureus infection promoted the release of MMP-2, MMP-9, TIMP-1, and Th2 cytokines, including IL-5, IL-13, and eotaxin." (PMID 33477617, 2021). "Staphylococcal protein A (SpA), a virulence factor from S. aureus, coupled to immunoglobulins in immune complexes, induces IL-10 production and suppresses staphylococcal enterotoxin B-induced IL-5, IL-13, IFN-γ and IL-17 production by nasal polyp cells." (PMID 35008843, 2021). "Indeed, the effect of IL-4/IL-13 and IL-5 on nasal epithelial repair was already showed but to date, no study has precisely described the role of IL-6, IL-9 and IL-10 (new ILs described in nasal polyposis) on human nasal epithelial cells in an in vitro wound repair model." (PMID 32209102, 2020). "In the clinical trial of the anti-IL-5 mAb, mepolizumab, there was significant improvement in the nasal polyposis severity, VAS score, endoscopic nasal polyp score, and all individual VAS symptom scores in the mepolizumab compared with placebo groups." (PMID 30778348, 2019). "The cytokine profile of nasal polyps in N‐ERD patients shows the typical components of a Th2 disease, as well as eosinophilia and significant upregulation of IL-4 and IL-5." (PMID 29564208, 2018). "Comparison of cytokine levels with relative abundance of bacteria in the nasal polyps tissues revealed that ECP and IL-5 were negatively correlated with the phylum Actinobacteria (p < 0.05, r = −0.3652, and −0.3760 respectively)." (PMID 29784985, 2018).
nasal polyps (continued). "The superantigens induce secretion of interleukin-5, eosinophil cationic protein, and immunoglobulin E, which play a pivotal role in the pathogenesis of CRS with nasal polyps." (PMID 27907108, 2016). "Total IgE correlates significantly with IL-5, ECP, LTC4/D4/E4, and sCD23 and with the number of eosinophils in nasal polyps." (PMID 25379119, 2014). "Stimulation of nasal tissue explants originating from inferior turbinate or nasal polyp tissue with the superantigen SEB for 24 hours stimulated the release of TH1 and Th 2 cytokines (IFN-γ, IL-2, IL-4, IL-5, IL-10, and IL-13)." (PMID 23282714, 2010). "The lymphocytes that infiltrate nasal polyps have been identified as predominantly memory T cells in an activated state and these produced a mixed Th1/Th2 cytokine pattern (IFN-gamma and IL-5)." (PMID 20214821, 2010). "The lymphocytes that infiltrate nasal polyps have been defined to be predominantly memory T cells in an activated status and produced a mixed Th1/Th2 cytokine pattern (IFN-gamma and IL-5)." (PMID 16551346, 2006). "Dupilumab can also improve nasal polyposis and dermatitis, conditions that IL-5-targeting agents generally do not directly treat." (PMID 40843371, 2025). "The often-proposed differentiation of patients with nasal polyps into non-allergic individuals with elevated blood eosinophils for choosing anti-IL-5 therapy, and allergic patients for anti-IgE treatment, is not supported by evidence." (PMID 38367543, 2024). "They hypothesized based on their study findings that when stimulated by IL-5, EDN degranulation promotes MMP-9 secretion from the nasal epithelium, possibly accounting for nasal tissue remodelling and subsequently nasal polyposis." (PMID 36832203, 2023). "A consensus statement proposed an algorithm based on BEC (300/150 cell/μL), FeNO (<25 ppb), and lack of nasal polyps and no anti-IL5 treatment to identify likely non-eosinophilic asthma, but the stability of the included features was not assessed." (PMID 37509154, 2023). "In agreement with that finding, we have observed a positive correlation between very low IL-22 and low IL-5 with the absence of nasal polyps in Cluster-2." (PMID 35455762, 2022). "In nasal polyp tissue, S. aureus can directly induce the release of the epithelial cell-derived cytokines TSLP and IL-33 by binding to TLR 2, thereby potentially propagating the expression of type 2 cytokines IL-5 and IL-13 in nasal polyp tissue." (PMID 35878202, 2022). "The exact pathophysiology of nasal polyposis is not completely explained, but recent studies demonstrated that it involves cytokines such as IL-5, IL-4 and IL-13." (PMID 35630042, 2022). "However, non-ECRSwNP is more common in Asian populations, which have lower levels of IL-5 and increased levels of the type 1 cytokine IFN-γ when compared to nasal polyps from European patients." (PMID 35697826, 2022). "The occurrence of nasal polyps and mucosal oedema in intranasal inspection was significantly reduced in the anti-IL5/IL5R group (p = 0.038 and p = 0.004 respectively) but not in the anti-IgE group." (PMID 32467765, 2020). "Notably, it has been reported that SEB not only enhances Th2 response through interaction with TLR2 signaling but also plays a potential role in IL-5, IL-13, and RANTES production in dispersed nasal polyps following the development of CRSwNP." (PMID 30764556, 2019). "When cultured nasal polyps are subjected to various in vitro treatments, only antibodies directed against IL-5 (but not IL-3 or GM-CSF) induce eosinophil apoptosis and deplete tissue eosinophils." (PMID 29682504, 2018). "IL-5, IL-6, and IL-10 levels were significantly increased in asthmatic patients with nasal polyps compared with non-asthmatic patients with nasal polyps." (PMID 29564208, 2018). "Patients whose nasal polyp score decreased had significantly higher baseline IL-5 levels in nasal secretions than non-responders." (PMID 29682504, 2018).